CDC37 (cell division cycle 37, HSP90 cochaperone)
Diseases named in the same sentence as CDC37 in open-access papers (continued):
Sharing a sentence is not in itself a finding about the gene and the disease.
multiple myeloma (4 papers, 2011 to 2021). "In multiple myeloma cells, apigenin disrupts the Hsp90–Cdc37–client complex, induces the degradation of multiple kinase clients, and decreases phosphorylation of Cdc37." (PMID 34685574, 2021). "Cdc37 is overexpressed in several types of cancers, including multiple myeloma." (PMID 21871133, 2011).
Alzheimer disease (3 papers, 2023 to 2024). A progressive, neurodegenerative disease characterized by loss of function and death of nerve cells in several areas of the brain leading to loss of cognitive function such as memory and language. "Therefore, Cdc37 has been identified as a potential target in neurological disorders such as Alzheimer’s disease and PD." (PMID 39273702, 2024).
prostate adenocarcinoma (3 papers, 2016 to 2020). "Overexpression of Cdc37 has been observed in prostate adenocarcinoma, where it collaborates with c-Myc and cyclin D1 in the transformation of this tumor." (PMID 27713878, 2016). "The second mechanism involves overexpression of chaperone Cdc37, an oncogene that is overexpressed in cancers such as prostate adenocarcinoma, where it collaborates with ERK5 to promote cell proliferation." (PMID 27713878, 2016). "Remarkably, in vitro evidences suggest that Cdc37 collaborates with ERK5 to promote proliferation of PC3 prostatic adenocarcinoma cells." (PMID 27713878, 2016). "This logic is consistent with elevated expression of CDC37, a kinome chaperone, in CRPC as compared to prostate adenocarcinoma and with the anti-tumor effect of the triple chaperone depletion." (PMID 32204513, 2020). "Co-expression correlation was found between MZF1 and CDC37 in CRPC patient samples (Spearman’s rank correlation score: 0.78) and in prostate adenocarcinoma patient samples (Spearman’s correlation: 0.41)." (PMID 31181782, 2019). "Cell division control 37 (CDC37), a key co-chaperone for HSP90, is highly expressed in castration-resistant prostate cancer (CRPC) cells as compared to normal prostate epithelial cells or prostate adenocarcinoma cells." (PMID 32204513, 2020). "Indeed, CDC37, the protein kinase-specialized (kinome) co-chaperone of HSP90, was highly expressed in the CRPC cells as compared to the prostate adenocarcinoma cells and normal prostate epithelial cells." (PMID 32204513, 2020). "We here used DU-145 prostate adenocarcinoma cells, in which endogenous CDC37 level was not fully induced as compared to the PC-3 cells." (PMID 32204513, 2020).
COVID-19 (2 papers, 2023 to 2024). A disease caused by infection with severe acute respiratory syndrome coronavirus 2. "At the genetic level, COVID-19 hospitalization and MS share five risk genes within two loci, including TNFAIP8, HSD17B4, CDC37, PDE4A, and KEAP1, which may mediate the association between MS and COVID-19." (PMID 37395896, 2023). "We subsequently identified two groups of specific DEPs: PPP2R5E, SGK3, CDC37, TSC2, and 20 other DEPs that were upregulated- or downregulated solely in the COVID-19 group, with no observed differences in the PQ group." (PMID 39301288, 2024).
hepatocellular carcinoma (2 papers, 2014 to 2025). A malignant tumor that arises from hepatocytes. "The molecular co-chaperone CDC37 is over-expressed in hepatocellular carcinoma (HCC) cells, where it functions with HSP90 to regulate the activity of protein kinases in multiple oncogenic signaling pathways that contribute towards hepatocarcinogenesis." (PMID 25051375, 2014).
hypoglycaemia (2 papers, 2021 to 2023). "CDC37 (RFU): 254.0 ± 4.8 vs 279.6 ± 6.55, 0.5-h post-hypoglycemia vs baseline, p < 0.01; 255.1 ± 5.0 vs 279.6 ± 6.55, 1-h post-hypoglycemia vs baseline, p < 0.01; 222.5 ± 7.7 vs 279.6 ± 6.55, 2-h post-hypoglycemia vs baseline, p < 0.01; 245.5 ± 6.7 vs 279.6 ± 6.55, 4-h post-hypoglycemia vs baseline." (PMID 34426634, 2021). "Interestingly, this effect was lost when STZ-diabetic mice were recovered to euglycaemia; however, CDC37 was also suppressed in non-diabetic mice recovered from hypoglycaemia to hyperglycaemia, suggesting that post-hypoglycaemic hyperglycaemia suppresses CDC37." (PMID 37015997, 2023).
liver cancer (2 papers, 2021). An epithelial or non-epithelial malignant neoplasm that arises from the liver. "As well, CDC37 silencing also mediates the arrest of cell cycle progression in liver cancer." (PMID 33976724, 2021).
lymphoma (2 papers, 2015 to 2017). A malignant (clonal) proliferation of B- lymphocytes or T- lymphocytes which involves the lymph nodes, bone marrow and/or extranodal sites. "In addition, we detected the presence of a known specific phosphorylated target of CK2 (phospho-Ser13 on CDC37) in lymphoma cells, which provides further evidence of CK2 active status as compared to normal B cells." (PMID 25788269, 2015).
oral cancer (2 papers, 2020 to 2022). "This was also the case in oral cancer where EVs derived from metastatic oral cancer cells promoted cell migration and invasion but triple KD of Hsp90α/Hsp90β/Cdc37 reversed these effects." (PMID 36060252, 2022). "The results of the research show that triple depletion of the interacting complex CDC37/HSP90α/HSP90β reduces the pro-malignant activity of oral cancer cells." (PMID 32867142, 2020). "According to the authors of the revolutionary research, triple silencing mediated by CDC37/HSP90α/HSP90β siRNA reduced EMT in oral cancer cells." (PMID 32867142, 2020).
asthma (1 paper, 2022). "Nineteen differentially expressed PRGs were included in the mild-to-moderate and severe asthma samples, among which CAPN1, NLRP1, TRIM31, NOS2, and CDC37 showed the highest difference (P<0.01)." (PMID 35967302, 2022).
Autoimmunity (1 paper, 2025). The occurrence of an immune reaction against the organism's own cells or tissues. "Beyond autoimmunity, our analysis identified genes with dual roles in AIDs and cancer, such as CDC37, DDX6, and MAPT, suggesting possible immune–oncogenic links." (PMID 40429780, 2025).
chronic myeloid leukemia (1 paper, 2024). "Moreover, bosutinib, a tyrosine kinase inhibitor, is perhaps the best candidate identified, as it is already in use against chronic myeloid leukemia and was found to target five upregulated proteins (CDC37, CDKN1B, GRB2, RASSF1, and SMAD2)." (PMID 39202022, 2024).
colorectal adenocarcinoma (1 paper, 2025). The most common type of colorectal carcinoma. "It was found that elevated expression of RPL31, CCT2, RPL17, and NUP85, as well as downregulation of NUP98, CDC37, DNM2, and SNRPN resulted from corresponding μ-ASOs treatment, correlating with improved survival in colorectal adenocarcinoma patients according to the TCGA database." (PMID 41373892, 2025).
glioblastoma (1 paper, 2011). The most malignant astrocytic tumor (WHO grade IV). "Cdc37 Ser13 phosphorylation in glioblastoma tumors was also significantly reduced in mice injected with compound 4 suggesting that at least part of the antitumoral effect of this class of inhibitors could involve inhibition of Cdc37." (PMID 22184283, 2011).
malaria (1 paper, 2022). Malaria is a serious and sometimes fatal disease caused by a parasite that commonly infects a certain type of mosquito which feeds on humans. "Validation of at least one PfHsp90 kinase client would subsequently support efforts to determine whether or not Cdc37 exists in the malaria parasite." (PMID 35892329, 2022).
metastatic colorectal cancer (1 paper, 2024). "Patients with CDC37-high metastatic colorectal cancer benefited more from anti-VEGF therapy." (PMID 39744132, 2024).
ovarian carcinoma (1 paper, 2022). A malignant neoplasm originating from the surface ovarian epithelium. "Celastrol altered the proliferation and cell cycle of ovarian cancer cells by interacting with CDC37." (PMID 35370699, 2022). "In our study, celastrol directly interacted with CDC37 to treat ovarian cancer." (PMID 35370699, 2022). "Thus, celastrol might alter the ovarian cancer cell proliferation and cell cycle by interacting with CDC37." (PMID 35370699, 2022). "In ovarian cancer, c-MYC, CDC37, and FN1 play essential roles in the initiation and progress of ovarian cancer." (PMID 35370699, 2022). "In addition to MYC, CDC37, and FN1, we discovered that celastrol regulated inflammatory pathways in ovarian cancer." (PMID 35370699, 2022).
psoriasis (1 paper, 2026). An autoimmune condition characterized by red, well-delineated plaques with silvery scales that are usually on the extensor surfaces and scalp. "Moreover, immunofluorescence of HSP90AB1 and CDC37 in psoriasis patients’ sections displayed higher intensity and colocalization when compared with the normal population." (PMID 41114929, 2026). "Thus, we hypothesized that the HSP90AB1 and co‐chaperone CDC37 complex might be a novel target in future psoriasis treatment." (PMID 41114929, 2026). "Here, we analyzed positive cell numbers of HSP90AB1 and CDC37 from 13 psoriasis patients and 4 negative controls." (PMID 41114929, 2026).
tauopathy (1 paper, 2024). Neurodegenerative disorders involving deposition of abnormal tau protein isoforms (tau proteins) in neurons and glial cells in the brain. "Thus, where it has been reported that the cellular levels of CDC37 appear to increase with age, this suggests that an imbalance between clearance and preservation of tau may occur that favors tau stability, which could lead to a tauopathy in time." (PMID 39615785, 2024). "Clearly, the role of CDC37 and CDC37L1 in tauopathies requires more attention." (PMID 39615785, 2024).
viral infection (1 paper, 2023). "There were some reports that the inhibition of the interaction of HSP90A with TBK1, IRF3, and Cdc37 impairs the innate immune response to viral infection." (PMID 37442062, 2023).
cancer (59 papers, 2006 to 2025). A tumor composed of atypical neoplastic, often pleomorphic cells that invade other tissues. "Surprisingly, we found that all these Cdc37/Hsp90 binding segments were frequently mutated in cancer genomes and most prominent non-V600 mutations occurred on or around these segments." (PMID 39897565, 2025). "CDC37 is frequently overexpressed in multiple cancer types to promote the maturation of mutated or overexpressed protein kinases." (PMID 41371342, 2025). "Cell division cycle 37 (Cdc37) is another such co-chaperone, and it is mostly linked to the formation of tumors due to its association with mutant kinases that drive cancer progression." (PMID 34638658, 2021). "We foresee new opportunities for improved Hsp90/Cdc37 interface inhibitors in cancer and other aging-associated diseases." (PMID 33672199, 2021). "The relevance of this new mechanism relays on the fact that Cdc37 acts as an oncogene, stabilizing other oncogenes that are mutated or overexpressed in cancer cells such as Akt, Her-2, or BRAF." (PMID 27713878, 2016). "Membrane associated HSP90 can activate HER-2 and also interact with Cdc37 leading to increased invasiveness of cancer cells." (PMID 26334999, 2015). "Recent studies have shown that treatment with Cdc37 siRNA compromised the maturation of Hsp90/Cdc37 clients, mediated an increased loss of proteins required for growth and survival and enhanced the sensitivity of cancer cells to Hsp90 inhibitors." (PMID 21871133, 2011). "Our data collectively reveal the mechanisms underlying braftide-triggered apoptosis in multiple cell lines, highlighting the therapeutic potential of targeting client kinase–CDC37 interactions in cancer cells." (PMID 41371342, 2025). "The genes BLK, CDC247, CSK, IRF5, STAT1, STAT4, and TNIP1 are associated with AIDs, and CDC37, DDX6, HSPA6, MAPT, PPIB, STAT1, and STAT4 are associated with cancers." (PMID 40429780, 2025). "The genes BLK, FAM167A, STAT1, STAT4, TNPO3, and TNIP1 are associated with AIDs, and CDC37, DDX6, MAPT, STAT1, STAT4, and UBE3A are associated with cancers." (PMID 40429780, 2025). "Among these, the interaction with Cdc37 is uniquely specialized for protein kinase clients, making it a particularly attractive and selective target for cancer therapy." (PMID 40491798, 2025). "Cdc37 has been tested for its ability to target cancer and appears to be very effective at least in prostate cancer." (PMID 38956273, 2024). "Among these proteins, p50/Cdc37 has been shown to be highly expressed in most cancers and is needed for the maturation of a wide range of oncogenic protein kinases." (PMID 38956273, 2024). "Like Hsp90, the expression levels of Cdc37 are increased in cancer cells, making Hsp90–Cdc37 PPI particularly intriguing for the design of potential cancer growth inhibitors." (PMID 39239280, 2024). "What’s more, heat shock protein 90 (HSP90) cooperates with its co-chaperone cell division cycle 37 (CDC37, highly expressed in endothelial cells) to support multiple protein kinases involved in cancer progression, including BRAF." (PMID 38233802, 2024). "High expression of CDC37 and HSP90 is a cause of malignant exosome secretion, and siRNA targeting CDC37 and HSP90 inhibited exosome secretion in carcinomas." (PMID 36671802, 2023). "While the Hsp90 isoform levels vary in tumors, and sometimes correlate with drug resistance or tumor stage, high expression levels of Cdc37 are more consistently found in proliferating cancer cells." (PMID 33672199, 2021). "We recently showed that the related conglobatin A, a protein–protein interface inhibitor of the interaction between the N-terminus of Hsp90 and its cochaperone Cdc37, blocks cancer stem cell properties by selectively inhibiting K-Ras4B but not H-Ras." (PMID 34199986, 2021). "In the light of the anti-cancer and anti-aging potential of Hsp90 inhibitors, Hsp90/Cdc37 interface inhibitors warrant further development, given their potentially low on-target toxicity." (PMID 33672199, 2021).
cancer (continued). "Studies have suggested that HSP90AA1, HSP90AB1 gene products, and their associated chaperon proteins (Aha1, Cdc37, p23, and Tpr2) as well as HSP90-dependent transcription factor HSF1 are overexpressed in a variety of cancers." (PMID 34109171, 2021). "Cdc37 was previously reported as an overexpressed oncogene that mediates carcinogenesis by stabilizing the oncogenic kinases in a number of cancers." (PMID 32139666, 2020). "Here, we show that MEK5 or overexpression of Cdc37—mechanisms that increase nuclear ERK5—induced ERK5 Small Ubiquitin-related Modifier (SUMO)-2 modification at residues Lys6/Lys22 in cancer cells." (PMID 32209980, 2020). "Our studies on CDC37 are ultimately aimed at targeting this factor in cancer as an alternative to HSP90." (PMID 31181782, 2019). "The cell division control 37 (CDC37) protein plays a fundamental role in chaperoning the protein kinase family and participates in cancer by maintaining the activity of protein kinases involved in cell proliferation and transformation." (PMID 31181782, 2019). "Withaferin A has been suggested to exert its anti-cancer properties through direct inhibition of HSP90/Cdc37 chaperone activity, induction of heat shock response and apoptosis following oxidative response in many cancer models." (PMID 29581860, 2018). "This profile is characteristic for some types of cancer cells, whose rapid growth requires up-regulation of chaperones (CDC37, heat shock proteins (HSPs) and CCTs) to prevent the accumulation of misfolded proteins that would trigger apoptosis." (PMID 29581850, 2018). "Recent studies have reaffirmed a central role of Cdc37 in chaperoning of kinase clients as silencing of Cdc37 function in cancer cells dramatically reduces binding of oncogenic kinase clients with Hsp90." (PMID 29267381, 2017). "We find that cancer-associated p16INK4a mutations differ in their modes of action toward CDK4 and CDK6 and in their abilities to displace CDK4 and CDK6 from Cdc37." (PMID 29091774, 2017). "Thirdly, over-expression of CDC37 has been reported in various cancers such as prostate cancer, multiple myeloma, anaplastic large cell lymphoma, acute myelocytic leukaemia, and HCC." (PMID 25051375, 2014). "Hsp70 cochaperones Bag1, Bag3, and Hop play significant roles in the etiology of some cancers as do Hsp90 cochaperones Aha1, p23, Cdc37, and FKBP1." (PMID 24278769, 2013). "Western blot analysis using anti- HSP90 revealed that mAb 4C5 specifically disrupts the surface interaction of Cdc37 with HSP90 in both cancer cell lines used." (PMID 22912728, 2012). "Our study reinforces existing reports regarding the oncogenic role of Cdc37 and its value as a target for cancer therapy." (PMID 22912728, 2012). "This study has proved the possibility of targeting the interaction of Hsp90 and its co-chaperones such as CDC37, Aha1 and p23 as a way to treat cancers." (PMID 24280675, 2012). "In particular, Cdc37, is increased in proliferating tissues, and is heavily expressed in certain cancers including anaplastic large cell lymphoma acute myelocytic leukaemia, hepatocellular carcinoma and multiple myeloma." (PMID 22912728, 2012). "More specifically, a 57.7% and 35.8% inhibition of cancer cell motility was obtained when 200 μg/ml of anti-Cdc37 was included in the culture medium of MDA-MB-453 and MDA-MB-231 cells respectively." (PMID 22912728, 2012). "Because the function of Hsp90/Cdc37 determines the stability and activity of these kinases, the dependency of the cancer cell kinome on Hsp90/Cdc37 makes the CK2-Cdc37-Hsp90 trinity a promising anti-cancer drug target." (PMID 21871133, 2011). "By promoting activities of several oncokinases, the Cdc37/Hsp90 chaperone complex contributes to the acceleration of cell proliferation observed in cancer cells." (PMID 22184283, 2011). "Notably, CDC37 is largely dispensable in most normal tissues, offering a potential therapeutic window for anti-CDC37 cancer therapies." (PMID 41371342, 2025).